CD2 (CD2 molecule)
Diseases named in the same sentence as CD2 in open-access papers (continued):
Sharing a sentence is not in itself a finding about the gene and the disease.
thymic lymphoma (3 papers, 1997 to 2023). "Briefly, Runx2 neutralizes the pro-apoptotic effect of Myc overexpression and confers a potent survival advantage to thymic lymphomas in Runx2/Myc-ERTM mice (CD2-Runx2 mice crossed with CD2-Myc-ERTM mice)." (PMID 36831211, 2023). "Transgenic mice expressing the c-myc proto-oncogene under the control of the CD2-dominant control region show stochastic development of mainly clonal thymic lymphoma with long latency, indicating that cooperative events are needed for the development of the fully malignant phenotype." (PMID 9310239, 1997).
adult T-cell leukemia/lymphoma (2 papers, 2022 to 2023). A peripheral (mature) T-cell neoplasm linked to the human T-cell leukemia virus type 1 (HTLV-1), adult T-cell leukemia/lymphoma is endemic in several regions of the world, in particular Japan, the Caribbean, and parts of Central Africa. "Adult T-cell leukemia/lymphoma (ATLL) cells showed typical irregular nuclear contours and were characterized by moderate CD2, CD4, and CD5, loss of surface CD3, CD7, and CD26, and dim-to-negative CD279." (PMID 35299754, 2022). "CD2 is expressed in a wide variety of T-cell malignancies, including T-ALL, SS (Sezary Syndrome), peripheral T-cell malignancies, and adult T-cell leukemia/lymphoma (ATL)." (PMID 37798328, 2023).
Alzheimer disease (2 papers, 2021 to 2024). A progressive, neurodegenerative disease characterized by loss of function and death of nerve cells in several areas of the brain leading to loss of cognitive function such as memory and language. "Conversely, for hub genes identified from upregulated DEGs, Alzheimer’s disease has been linked to CD2, CDC25A, CKS2, LCK, PRKACG, and S100A7." (PMID 39766348, 2024). "The major novelty of this study is demonstrating that the expression of cyclin D2 (cD2) is uniformly decreased in all tested conditions related to the pathomechanism of Alzheimer’s disease (AD), including Aβ toxicity, neuroinflammation and human post-mortem brain tissue from AD patients." (PMID 34793515, 2021).
bladder cancer (2 papers, 1999 to 2008). "The present studies show that keratin 6a is induced in UROtsa cells malignantly transformed by Cd2+ or As3+ and that keratin 6a overexpression also occurs in high-grade human bladder cancer." (PMID 18414623, 2008). "The other goals of the study were similarly reached when it was shown the keratin 6a was expressed in tumor heterotransplants generated from the Cd2+- and As3+-transformed cells and that keratin 6a was overexpressed in some archival patient specimens of high-grade bladder cancer." (PMID 18414623, 2008). "Our goals were to verify overexpression of keratin 6a in Cd2+- and As3+-transformed UROtsa cells, the corresponding tumor heterotransplants, and human bladder cancer biopsy specimens and to assess what factors may be involved in keratin 6a overexpression." (PMID 18414623, 2008).
celiac disease (2 papers, 2009 to 2018). An autoimmune genetic disorder with an unknown pattern of inheritance that primarily affects the digestive tract. "γδIELs, αβIELs, and CD2+CD7+IELs isolated from intestinal biopsies of children with active coeliac disease and treated coeliac disease were also analysed for expression levels of preTα mRNA." (PMID 18299319, 2009). "The preTα mRNA expression levels were significantly lower in the CD2+CD7+IELs of patients with coeliac disease, both in active and inactive disease, as compared to controls." (PMID 18299319, 2009). "However, we showed in our study that despite strict adherence to the diet, about 50% of children with celiac disease (CD2) had relatively low TAC levels and high TOC levels, which would indicate oxidative stress." (PMID 29854070, 2018).
chronic periodontitis (2 papers, 2021 to 2022). A chronic inflammatory process that affects the tissues that surround and support the teeth. "It was concluded that L. brevis CD2 could be used as an alternative to antibiotics to treat aggressive periodontitis, without the risk of promoting antibiotic resistance." (PMID 35402306, 2022). "They recruited 18 patients with aggressive periodontitis and divided them into 3 groups after SRP, which were given L. brevis CD2, L. brevis CD2 with doxycycline, or doxycycline alone for 14 days." (PMID 35402306, 2022).
Crohn disease (2 papers, 2022 to 2023). A gastrointestinal disorder characterized by chronic inflammation involving all layers of the intestinal wall, noncaseating granulomas affecting the intestinal wall and regional lymph nodes, and transmural fibrosis. "During Crohn’s disease, in addition to its stage, we observed significantly lower concentrations of β-endorphin compared to the concentration in the control group of 47.2 (34.4–57.5) pg/mL (p = 0.007 between CD1 and C and p < 0.0001 in both the CD2 and CD3 groups versus the control group (C))." (PMID 37509676, 2023). "These samples correspond to six participants diagnosed as non-IBD (nIBD1 and nIBD2), Crohn’s disease, (CD1 and CD2) and ulcerative colitis, (UC1 and UC2), which were followed for 1 year each." (PMID 36304282, 2022).
diabetic nephropathy (2 papers, 2013 to 2025). "The expression levels of IL7R, CD2, GZMA, CD3D and FCER1A significantly differed between diabetic nephropathy and controls." (PMID 41332907, 2025).
gingivitis (2 papers, 2021 to 2023). A disorder involving inflammation of the gums; may affect surrounding and supporting structures of the teeth. "The short-term effect (60 days) of Lactobacillus brevis CD2 lozenges vs placebo on variables related to caries and gingivitis in type 1 diabetic children was evaluated." (PMID 33083852, 2021).
Granuloma (2 papers, 2011 to 2015). A compact, organized collection of mature mononuclear phagocytes, which may be but is not necessarily accompanied by accessory features such as necrosis. "In the TT, BT, and R1 forms, a large number of lymphocytes in the periphery and within granulomas, perivascular space, nerves, and interstitium showed expression of CD2." (PMID 26635870, 2015). "Consistent with this, T cells and NK cells were typically localized in the peripheral corona zone of caseous granulomas as assessed by CD2 immunostaining." (PMID 22114556, 2011).
head and neck squamous cell carcinoma (2 papers, 2023 to 2024). A squamous cell carcinoma that arises from any of the following anatomic sites: lip and oral cavity, nasal cavity, paranasal sinuses, pharynx, larynx, and salivary glands. "This outcome is equivalent to a study’s findings, which showed that one probiotic, Lactobacillus brevis CD2, had decreased the incidence of radio chemotherapy-induced OM (grades 3 and 4) in patients with head and neck squamous cell carcinoma who were receiving chemoradiation therapy." (PMID 37242437, 2023).
hyperglycaemia (2 papers, 2018 to 2022). "Probably in patients with CD2 at early stage of disease development, hyperglycemia can increase the availability of the additional substrates for glycolytic processes that promote normalization of energy supply of metabolic reactions in pathological cells." (PMID 30116733, 2018).
inflammatory skin disease (2 papers, 2022). Inflammatory skin disorders covers a broad category that includes many conditions ranging in severity, from mild itching to grave medical health complications These disorders are common in people of all ages and races. "This may at least in part explain the divergent effects observed when treating inflammatory skin diseases with antibodies to CD6 versus CD2." (PMID 36353616, 2022). "Moreover, our findings may provide a molecular basis for selective interference with either CD6/CD166/CD318, or CD2/CD58, or both to specifically treat different types of inflammatory skin diseases." (PMID 36353616, 2022).
influenza (2 papers, 2012 to 2025). An acute viral infection of the respiratory tract, occurring in isolated cases, in epidemics, or in pandemics; it is caused by serologically different strains of viruses (influenzaviruses) designated A, B, and C, has a 3-day incubation period, and usually lasts for 3 to 10 days. "By comparing the areas under the ROC curves we took both measures -sensitivity and specificity- into account and found comparable and most favourable results for CD2 and CD3, at least during the period with significant influenza circulation." (PMID 22452874, 2012).
large granular lymphocyte leukemia (2 papers, 2022 to 2025). "The EBT-8 cell line was established from a large granular lymphocyte leukemia of T cell origin and shows surface expression of CD2, CD3, CD8, HLA-DR, and T cell receptor alpha/beta, which are characteristic of cytotoxic T lymphocytes." (PMID 40920775, 2025). "Typical immunophenotype of large granular lymphocytic leukemia (LGLL) included positive expressions of CD2, surface CD3 and CD8 (occasionally CD4), heterogeneous CD7, and over-/under-expression of CD5 but negative for CD25, CD26, and TCRγδ." (PMID 35299754, 2022).
leukocytosis (2 papers, 2014 to 2024). "CD2 identification in APL was strongly linked with high leukocytosis (P = 0.004), shorter time to relapse and high relapse rate (P = 0.03), and lower overall survival (P = 0.07) than in patients with APL with negative CD2 detection." (PMID 38861104, 2024). "Previous research has shown that CD2+ immunophenotypes in patients with APL are associated with leukocytosis and the hypogranular M3v phenotype, as well as a higher probability of thrombosis." (PMID 25045197, 2014). "Nonetheless, both CD2+ and CD34+ immunophenotypes are associated with leukocytosis, so differences in clinical outcomes between patients with CD2+ APL and CD2− APL or CD34+ APL and CD34− APL may be due to WBC counts and not because of CD2+ or CD34+ expression." (PMID 25045197, 2014). "Moreover, both the research findings and available literature have shown an association between leukocytosis and CD2, CD34, and CD56 expression." (PMID 25045197, 2014).
lymphopenia (2 papers, 2008 to 2013). Reduction in the number of lymphocytes. "Unfortunately, the therapeutic potential of agonists of the CD3/CD28/CD2 signaling pathway is uncertain, given the plethora of undesirable side effects, including transient lymphopenia, previously observed in patients treated with OKT3 antibodies." (PMID 24385908, 2013). "Systemic immune aberrations in ALS patients include alterations in macrophage activation profiles, elevated levels of complement proteins in sera, increased IL-13 producing T cells and circulating neutrophils, lymphopenia with reduced number of CD2+ and CD8+ T cells." (PMID 18648532, 2008).
malaria (2 papers, 2016). Malaria is a serious and sometimes fatal disease caused by a parasite that commonly infects a certain type of mosquito which feeds on humans. "CD2 includes Alitretinoin combined with Mefloquine, employed to treat malaria, which may prevent glia activation and glutamate excitotoxicity." (PMID 26807587, 2016).
malignant non-Hodgkin’s lymphoma (2 papers, 2022). "In that study, the flow cytometry characterization of 138 CSF samples from patients suffering from non-Hodgkin lymphoma, and negative for leptomeningeal infiltration (LM−), showed that CSF is a tissue rich in CD2−, CD3− and CD5− positive T lymphocytes." (PMID 35053611, 2022).
microcephaly (2 papers, 2021 to 2022). A congenital or acquired developmental disorder in which the circumference of the head is smaller than normal for the person's age and sex. "Loss of either cD2 or cD1 in mouse results in smaller forebrains (microcephaly), but only Ccnd2 null mice (cD2−/−) show selectively affected specific neuronal subtypes." (PMID 33613193, 2021).
mycobacterial infection (2 papers, 2021 to 2022). "The role of the remaining 7 genes (CD2, CD6, CD247, ZAP70, CD3D, SH2D1A, and CD3E) in T-cell signaling and modulation of host immune responses in mycobacterium infections is also supported." (PMID 35198572, 2021).
mycosis fungoides (2 papers, 2022 to 2025). Classical mycosis fungoides is the most common type of mycosis fungoides (MF), a form of cutaneous T-cell lymphoma, and is characterized by slow progression from patches to more infiltrated plaques and eventually to tumors. "This study explored the prognostic significance of immunohistochemical loss of T-cell antigens—specifically CD2, CD3, CD5, and CD7—in patients diagnosed with early-stage mycosis fungoides (MF)." (PMID 40981343, 2025). "This study aimed to determine whether immunohistochemical loss of T-cell markers CD2, CD3, CD5, and CD7 in patients with early-stage mycosis fungoides is associated with overall survival and progression-free survival." (PMID 40981343, 2025).
myeloid neoplasm (2 papers, 2025). Proliferation of myeloid cells originating from a primitive stem cell. "Immunohistochemically, positive staining for tryptase and CD117 (c-kit) confirm mast cell lineage, while CD25, CD30 and CD2 distinguish SM from reactive mastocytosis or other myeloid neoplasms." (PMID 39911853, 2025). "This rare condition typically presents with a specific immunophenotypic profile (CD117 + +, tryptase + +, CD11b −, CD123 −, CD2 −, CD25).While MML features can occur in various myeloid neoplasms, its presentation as a blast phase manifestation of CML is exceptionally rare." (PMID 40751871, 2025).
neuroblastoma (2 papers, 1993 to 2024). Neuroblastoma (NB) is the most common solid, extracranial childhood tumor. "We find that LFA-3 (CD58), the ligand for CD2 is of predominant importance in predicting susceptibility of neuroblastoma to the cytotoxic actions of NK and LAK cells, while expression of ICAM-1 (CD54) may also modify susceptibility." (PMID 8494726, 1993). "Engineered NK cells targeting GD2 act on the impaired activity of MDSCs when co-administered with CD2 targeted CAR T cells in a neuroblastoma model." (PMID 39835140, 2024).
psychosis (2 papers, 2018 to 2022). "Our results suggest that CD2-KO mice are a valuable model in translational research targeted at the pharmacoresistant cognitive symptom domain in causal relation to hippocampal over-activity in the prodrome-to-psychosis transition." (PMID 30301879, 2018). "In this study, the preclinical cD2-KO mouse model, displaying hippocampal-interneuron dysfunction, and causing hyperlocomotion, anhedonia, and impairments of the learning and working memory, may be useful in translational research on the pharmacoresistant cognitive symptom domain of psychosis." (PMID 35011697, 2022).
schizophrenia (2 papers, 2018 to 2022). A major psychotic disorder characterized by abnormalities in the perception or expression of reality. "To investigate this preclinically, we deployed the cyclin-D2 knockout mouse model (CD2-KO) that shares physiological and behavioral abnormalities with the schizophrenia prodrome, including a hyperactive CA1 region, and cognitive and affective deficits." (PMID 36225391, 2022). "Most relevant to schizophrenia is the finding, that CD2-KO mice are less efficient in their search strategies in the water-maze and in spatial forms of cognitive flexibility, while basic spatial learning is intact." (PMID 30301879, 2018). "Conducting a comprehensive phenotyping of CD2-KO mice, we found that they displayed novelty-induced hyperlocomotion (a rodent correlate of positive symptoms of schizophrenia), that was largely resistant against D1- and D2-dopamine-receptor antagonism, but responsive to the mGluR2/3-agonist LY379268." (PMID 30301879, 2018).
T-cell leukemia (2 papers, 2008 to 2023). A malignant disease of the T-lymphocytes in the bone marrow, thymus, and/or blood. "CD58-displaying BV bound to CD2-positive, but not CD2-negative Jurkat cells, a human T cell leukemia cell line." (PMID 19107192, 2008).
T-cell prolymphocytic leukemia (2 papers, 2019 to 2022). A slow-growing type of leukemia (blood cancer) in which too many lymphocytes are found in the bone marrow and/or blood. "T-cell prolymphocytic leukemia (PLL) cells were characterized by homogenously moderate CD2, CD5, and CD7, variable loss of surface CD3, moderate-to-dim CD26, heterogeneous CD25, and moderate TCL1." (PMID 35299754, 2022). "Marrow flow cytometry confirmed T-prolymphocytic leukemia with lymphocytes expressing CD2, CD3, CD7, CD52, and TCL-1." (PMID 31327318, 2019).
acute kidney injury (1 paper, 2026). Sudden and sustained deterioration of the kidney function characterized by decreased glomerular filtration rate, increased serum creatinine or oliguria. "Specific EV antigens were associated with key clinical outcomes: CD20 and CD2 levels differed between patients with or without infections (bacterial, viral, and fungal) developed during hospitalization; CD40 and CD146 were elevated in patients who developed acute kidney injury." (PMID 41683683, 2026).
alcohol (1 paper, 2006). "Consistent with this, we observed decreased expression of natural killer cell-related genes, including CD44, IL15R, CD2 and CCL5, in alcohol-associated cirrhotic liver samples." (PMID 17121680, 2006).
allergic asthma (1 paper, 2020). A asthma with a basis in a pathological type I hypersensitivity reaction. "In the current study, we investigated the role of CD2 in a murine model of allergic asthma using mice deficient in CD2 (Cd2−/−)." (PMID 32477356, 2020). "Given the established role of IL-13 in promoting goblet cell hyperplasia, lung inflammation and AHR in allergic asthma, our studies reveal a unique role for CD2 in the regulation of Th2-associated allergic asthma." (PMID 32477356, 2020). "While these studies provide a causal link between CD2 and asthma, the specific role of CD2 in allergic asthma remains to be defined." (PMID 32477356, 2020). "Mechanistically, we demonstrate that CD2 critically modulates gene expression of alarmins such as IL-25, IL-13 receptors (IL-13Rα1 and IL-13Rα2) and several microRNAs that have known roles in the pathogenesis of allergic asthma." (PMID 32477356, 2020).
anaplastic large cell lymphoma (1 paper, 2022). Anaplastic large cell lymphoma (ALCL) is a rare and aggressive peripheral T-cell non-Hodgkin lymphoma, belonging to the group of CD30-positive lymphoproliferative disorders, which affects lymph nodes and extranodal sites. "Of note, mast cells with anaplastic morphology and positive expression for CD2, CD25 and CD30 should be further evaluated to rule out anaplastic large cell lymphoma." (PMID 35884535, 2022).
asthma (1 paper, 2020). "Since only IL-13 (but not IL-4 or IL-5) expression was diminished in Cd2−/− HDME mice, our data demonstrate a specific regulation of IL-13 by CD2 in asthma." (PMID 32477356, 2020). "In contrast, HDME-treated Cd2−/− mice manifested a decreased AHR compared to similarly treated WT mice, suggesting that CD2 regulates AHR in HDME-induced asthma." (PMID 32477356, 2020). "CD2 gene transcripts were also significantly elevated in the lungs of these asthma patients, consistent with prior reports demonstrating that CD2 and its ligand CD58 is increased on monocytes and eosinophils of asthma patients." (PMID 32477356, 2020). "Surface expression of CD2 and its ligand, CD58, is increased on the monocytes and eosinophils of asthma patients, which correlate with elevated serum IgE levels, suggesting that CD2 may contribute to allergic airway inflammation." (PMID 32477356, 2020).
Behcet disease (1 paper, 2025). A chronic, relapsing, multisystemic vasculitis characterized by mucocutaneous lesions, as well as articular, vascular, ocular and central nervous system manifestations. "Furthermore, through multiomics data analysis and machine learning techniques, researchers identified CD247, CD2, and CCR7 as diagnostic biomarkers for AAA in Behcet's disease patients and developed a nomogram model for diagnosis." (PMID 40995065, 2025).
brain tumor (1 paper, 2022). "Additionally, the destructive properties of subventricular NPCs against GBM cells appeared dependent on the expression of D-type cyclins, in particular cyclin D1 (cD1) and cD2, genes that act as key brain tumor oncogenes." (PMID 35011697, 2022).